PLTP (phospholipid transfer protein)
Diseases named in the same sentence as PLTP in open-access papers (continued):
Sharing a sentence is not in itself a finding about the gene and the disease.
prediabetes (1 paper, 2024). "The literature review revealed T2D or prediabetes associations with 10 proteins, including PON3, PLTP, and SHBG." (PMID 39589852, 2024).
pulmonary hypertension (1 paper, 2021). Increased pressure within the pulmonary circulation due to lung or heart disorder. "Here, we identified 532 DEPs; several of these DEPs may be critical to CMS or pulmonary hypertension, including α-1-acid glycoprotein, collagen, fibulin, haptoglobin, PLTP, and TAGLN2." (PMID 34471201, 2021).
renal fibrosis (1 paper, 2023). A final common manifestation of a wide variety of chronic kidney diseases characterized by glomerulosclerosis and tubulointerstitial fibrosis. "Similarly, the urinary levels of PLTP and SLPI are both increased in CKD patients with renal fibrosis." (PMID 38027143, 2023).
Shock (1 paper, 2021). The state in which profound and widespread reduction of effective tissue perfusion leads first to reversible, and then if prolonged, to irreversible cellular injury. "Taken together, the previous reports and the present results strongly suggest that PLTP activity may adapt to and eliminate the culprit endotoxins in patients with septic shock." (PMID 34778311, 2021).
synovitis (1 paper, 2018). Inflammation of a synovial membrane. "Increased PLTP in the joint of RA patients could therefore directly target FLS, and participate in inflammation, joint destruction and synovitis observed in RA." (PMID 29565987, 2018).
tuberculosis (1 paper, 2025). A chronic, recurrent infection caused by the bacterium Mycobacterium tuberculosis. "The discovery of these six mRNAs (NEDD4, PLTP, RNASEL, SEMA7A, TAPBP, and THBS1) not only reveals critical molecular mechanisms underlying immune regulation in tuberculosis but also establishes a robust theoretical foundation for advancing diagnostic and therapeutic strategies." (PMID 40182927, 2025). "Based on these findings, we hypothesized that PLTP played a crucial role in lipid metabolism and immune cell recruitment in tuberculosis." (PMID 40182927, 2025). "The results showed that PLTP, RNASEL, SEMA7A, and TAPBP were upregulated in the whole blood of tuberculosis patients, while NEDD4 and THBS1 were downregulated." (PMID 40182927, 2025). "NEDD4, PLTP, RNASEL, SEMA7A, TAPBP, and THBS1 were combined into a 6-mRNA feature panel for diagnosis of tuberculosis." (PMID 40182927, 2025).
Venous thrombosis (1 paper, 2015). Formation of a blood clot (thrombus) inside a vein, causing the obstruction of blood flow. "No study has reported an assessment of the effects of PLTP on blood clotting reactions, such as reflected in thrombin generation assays, or on the association of venous thrombosis (VTE) risk with PLTP activity." (PMID 26185485, 2015).
tumor (17 papers, 2017 to 2025). "Regarding PLTP, the high-expression group had worse prognosis and higher infiltration of M2 macrophages and tumor-associated macrophages (TAMs) compared to the low-expression group." (PMID 35468826, 2022). "Encoding lipid transfer proteins, PLTP is important in tumor growth." (PMID 40308607, 2025). "We found that the mRNA expression CD68, CD69 and CYP27A1 levels were significantly downregulated, and PLTP levels was significantly up regulated in tumor samples." (PMID 37880277, 2023). "Fifteen distinct clusters were identified and five clusters (M_C1_PLTP, M_C3_CCL20, M_C4_CXCL10, M_C5_NBEAL1, and M_C12_CD207) were abundant in tumor." (PMID 35102420, 2022). "We show that enforced expression of PLTP potently suppresses colony formation in human tumor cell lines." (PMID 36309086, 2022). "While this protein is reported to be widely expressed in many cell types, we were unable to detect PLTP following nutlin treatment in several tumor cell lines, with the exception of HepG2." (PMID 36309086, 2022). "In conclusion, this study demonstrates that a high expression of MYO5A, PLTP, or TPP1 is associated with tumor progress and poor prognosis in GC patients." (PMID 32735728, 2020). "NRP2 and PLTP collectively enhance ECM remodelling, facilitating tumour invasion, as PLTP could supply necessary lipids for protease activity or membrane dynamics involved in invasion." (PMID 40134439, 2025). "Further macrophage subsets were identified based on their high expression of CD68, CD163, and MRC1 (encoding CD206), which could be denoted as resident tissue macrophages and segregated into normal colon epithelial tissue (NLRP3+ and phospholipid transfer protein PLTP+) or tumor tissue (IL1B+)." (PMID 34572013, 2021). "The described shift in correlation between PLTP and MMP14 highlights how tumour progression can fundamentally rewire cellular interactions and molecular pathways within the TME." (PMID 40134439, 2025). "PLTP was among the other significant proteins found in EBP, which is expressed in different types of neoplasms and is involved in cancer development." (PMID 36544145, 2022). "PLTP and MET have been identified as potential biomarkers for LUAD diagnosis and in the evaluation of successful tumor excision." (PMID 36544145, 2022). "RT–PCR confirmed higher expression of MYO5A, PLTP, PALM2‐AKAP2, and TPP1 in tumor tissue than in normal tissue specimens." (PMID 32735728, 2020). "Western blotting confirmed that protein expression of MYO5A, PLTP, and TPP1 was higher in tumor tissue than in normal tissue specimens." (PMID 32735728, 2020). "One month after removal of the LUAD, expression of MET, PLTP and MFAP5 all decreased, which could be attributed to the radical tumor removal." (PMID 36544145, 2022). "PLTP and MET were identified as potential biomarkers to evaluate successful tumor excision." (PMID 36544145, 2022). "Among the most significantly downregulated genes in tumor samples were AGBL5, SECISBP2, and PLTP, which are involved in protein deglutamylation, selenoprotein synthesis, and lipid metabolism, respectively, and their downregulation may impact platelet function and stability in cancer." (PMID 39001461, 2024). "One month after surgery, the three proteins, PLTP, MET and MFAP5, showed a decreasing trend, and when compared to patients without LUAD, the significance was no longer found, possibly indicating tumor removal." (PMID 36544145, 2022).
cancer (14 papers, 2020 to 2025). A tumor composed of atypical neoplastic, often pleomorphic cells that invade other tissues. "In terms of anti-cancer properties, one study found that PLTP is essential in mediating the association of triacyl lipid A with lipoproteins, resulting in an extension of its residence time and magnification of its proinflammatory and anticancer properties." (PMID 38022651, 2023). "Furthermore, PLTP has been linked to the diagnostic and anti-cancer actions of specific malignancies." (PMID 38022651, 2023). "We show that when exogenously overexpressed, PLTP is a potent suppressor of colony formation in cancer cells and that it plays a role in controlling the sensitivity of cells to ferroptosis." (PMID 36309086, 2022). "In this case, the assumption made for FINC, APOB and PLTP would be the opposite: cancer cells eliminate more PIK3IP1 protein in the urine, as a mechanism to down-regulate its expression, in order to survive." (PMID 31963743, 2020). "Such a wide range of cancer types with differential expression of PLTP indicate that PLTP may be an important regulator of some common processes related to tumors." (PMID 35468826, 2022). "RT–PCR, western blotting, and the CCK8 assay confirmed that MYO5A, PLTP, and TPP1 exhibited higher expression in GC tissue and were involved in promoting GC cancer cell proliferation." (PMID 32735728, 2020). "However, there is no definitive evidence on the correlation of PLTP with cancer patient survival in previous publications." (PMID 39075362, 2024). "Phospholipid transfer protein (PLTP), a widely expressed key lipid transfer protein, not only influences the transport of plasma triglycerides and cholesterol but also responds to pro-inflammatory stimuli and exhibits anti-cancer properties." (PMID 40182927, 2025).
cardiovascular disease (12 papers, 2008 to 2026). "Plasma phospholipid transfer protein (PLTP) is a risk factor for cardiovascular diseases." (PMID 39343001, 2024). "Additional support for this idea is provided by studies showing that PLTP deficiency is associated with anti-inflammatory effects, and by a study in which an association was found between PLTP activity and inflammatory markers in patients with cardiovascular disease." (PMID 18509527, 2008). "Phospholipid transfer protein (PLTP) is a lipid transfer protein classically studied in the context of plasma lipoprotein metabolism, high-density lipoprotein (HDL) remodeling, and cardiovascular disease risk." (PMID 42074254, 2026). "Recently, a positive relationship was established between PLTP activity and inflammatory markers in patients with cardiovascular disease or diabetes." (PMID 29731975, 2018). "Although PLTP was mostly studied for its role in lipid metabolism and cardiovascular disease, recent evidence suggests that it also plays a major role in inflammation and modulation of the immune response in the periphery." (PMID 29731975, 2018).
infection (9 papers, 2016 to 2024). The state of being infected such as from the introduction of a foreign agent such as serum, vaccine, antigenic substance or organism. "Furthermore, increased PLTP activity is associated with less tissue damage caused by bacterial infection, further highlighting the importance of a normal regulation of the PLTP during infection." (PMID 30842338, 2019). "Meanwhile, CCN3 and PLTP were upregulated in patients with longer periods of infection which are involved in the negative regulation of inflammation." (PMID 37047248, 2023). "Infection and inflammation are associated with changes in the activity of plasma proteins that regulate the HDL composition, such as lecithin cholesterol acetyltransferase (LCAT), phospholipid transfer protein (PLTP), and cholesteryl ester transfer protein (CETP) mainly." (PMID 27293313, 2016). "The present study sheds new light on the key role of PLTP in the defense against infection with gram-negative bacteria with two main properties of rhPLTP that should be considered and might act in a complementary manner." (PMID 28596518, 2017).
metabolic disorders (3 papers, 2021 to 2023). "This work highlights the relationship between PLTP, TRL metabolism and low-grade inflammation, as observed in metabolic diseases." (PMID 36362012, 2022). "Our results show that PLTP, by modulating the intestinal translocation of LPS and plasma processing of TRL-bound LPS, has a major impact on low-grade inflammation and the onset of diet-induced metabolic disorders." (PMID 36362012, 2022).
central nervous system diseases (1 paper, 2024). "The phospholipid transfer protein regulates the transfer of a number of lipid components between lipoproteins and cells, and its abnormal expression is associated with many lipid-related metabolic diseases as well as central nervous system diseases." (PMID 39519833, 2024).
respiratory diseases (1 paper, 2025). "Reduced PLTP production may decrease surfactant production and pulmonary immune responses and inflammation, which may be observed in cattle with respiratory diseases." (PMID 40822650, 2025).
PLTP also shares sentences with these, for which no sentence is quoted: lung carcinoma (4 papers); Ataxia (3); prostate carcinoma (3); bacterial infection (2); breast carcinoma (2); inflammation (2); abdominal aortic aneurysm (1); age-related macular degeneration (1); allergic rhinitis (1); Amoebiasis (1); angina (1); bladder cancer (1); Blindness (1); celiac disease (1); cerebral (1); Cerebral ischemia (1); chronic kidney disease (1); Cirrhosis (1); clear cell renal cell carcinoma (1); demyelinating disease (1); dilated cardiomyopathy (1); embryonal carcinoma (1); fibrosis (1); glioblastoma (1); Guillain-Barre syndrome (1); Hearing Loss (1); hepatocellular carcinoma (1); Hypercholesterolemia (1); hypothyroidism (1); Lewy body dementia (1).
A further 17 diseases each share a sentence with PLTP in 1 paper.